C1orf115 (chromosome 1 open reading frame 115)
Description:
Regulates drug efflux through modulation of ABCB1 localization and activity.
Synonyms: RDD1; FLJ14146
Tractability: Antibody: UniProt predicts a signal peptide or a membrane-spanning region. PROTAC: ubiquitination databases record sites on it.
Gene: Protein-coding gene on chromosome 1 (220,690,363 to 220,699,153, forward strand). Ensembl gene ENSG00000162817.
Subcellular location: Membrane
Gene Ontology:
Biological process: regulation of response to drug
Cellular component: 9+0 non-motile cilium; membrane
Genetic constraint (gnomAD): Loss-of-function variants: 16 observed, 6.54 expected, observed/expected ratio (o/e) 2.44. That is too few expected variants to judge how well the gene tolerates losing a copy. Missense variants: 237 observed, 164.13 expected, observed/expected ratio (o/e) 1.44, 90% interval 1.3 to 1.61. Synonymous variants: 109 observed, 78.35 expected, observed/expected ratio (o/e) 1.39, 90% interval 1.19 to 1.63.
Homologues: Orthologues: chimpanzee C1H1orf115 (100% identical), macaque C1H1orf115 (96% identical), pig C1orf115 (75% identical), rabbit C1orf115 (71% identical), rat C13h1orf115 (70% identical), mouse C130074G19Rik (70% identical), dog C1orf115 (68% identical), zebrafish zgc:194392 (27% identical), zebrafish si:dkey-126g1.9 (25% identical).
Diseases named in the same sentence as C1orf115 in open-access papers:
C1orf115 is named in the same sentence as 5 diseases in open-access papers, as found by Europe PMC text mining. Sharing a sentence is not in itself a finding about the gene and the disease. The quoted sentences say what the papers report.
cancer (5 papers, 2020 to 2024). A tumor composed of atypical neoplastic, often pleomorphic cells that invade other tissues. "It has been reported that the loss of C1orf115 can lead to the resistance to five anticancer drugs, and the low expression of C1orf115 is related to the poor prognosis of many cancers." (PMID 34306017, 2021). "Furthermore, little is known about the roles of ALDOB, CRYL1, and C1orf115 in human cancer, especially GC, so future studies on these genes are needed." (PMID 38737262, 2024). "Beyond that, little is known about the roles of MOGAT2 and C1orf115 in human cancers." (PMID 32256214, 2020).
tumor (1 paper, 2024). "PTGR1, C1orf115, CRYL1, ALDOB, and SULT1B1 may be tumor suppressor genes involved in GC progression." (PMID 38737262, 2024).
C1orf115 also shares sentences with these, for which no sentence is quoted: kidney cancer (1 paper); lung adenocarcinoma (1); sarcoma (1).